SLC3A2 (solute carrier family 3 member 2)
Diseases named in the same sentence as SLC3A2 in open-access papers (continued):
Sharing a sentence is not in itself a finding about the gene and the disease.
tumor (continued). "Mechanistically, IFNγ significantly downregulated the expression of SLC3A2 and SLC7A11, and then impaired the uptake of cystine by tumor cells, which resulted in enhanced lipid peroxidation and ferroptosis." (PMID 36033530, 2022). "Researchers believe that the main mechanism underlying this effect is that IFNγ released by CD8+ T cells downregulates the expression of SLC3A2 and SLC7A1 in tumor cells and inhibits the uptake of cystine by tumor cells." (PMID 34975326, 2022). "Recent studies have shown that the IFN γ released by CD8+ T cells downregulates the expression of SLC3A2 and SLC7A11 and impairs the uptake of cystine by tumor cells, thereby promoting lipid peroxidation and ferroptosis in tumor cells." (PMID 36233241, 2022). "The paper reported that CD8 + T cells downregulated the expression of SLC3A2 and SLC7A11 to promote tumor cell lipid peroxidation and ferroptosis." (PMID 34475496, 2021). "Studies have reported that SLC7A5, SLC1A5, SLC3A2, SLC43A1 and SLC43A2 are the major BCAA transporters in tumor cells." (PMID 33882453, 2021). "In particular, the amino acid transporters SLC1A5 and SLC7A5 as well as the ancillary subunit SLC3A2, which are required for efficient uptake of glutamine and leucine respectively, could strengthen the metabolic capabilities and effector functions of tumor-directed CAR-NK and T cells." (PMID 33953707, 2021). "CD8+ T cells enhance ferroptosis of tumor cells through releasing interferon gamma (IFNγ) and repressing the expression of SLC3A2 and SLC7A11 in tumor cells." (PMID 34733403, 2021). "CD8+ T cell-derived IFN-γ downregulated the expression of SLC3A2 and SLC7A11 by inhibiting its transcription, thus promoting lipid peroxidation and ferroptosis in tumor cells." (PMID 34764976, 2021). "The latest literature reported that CD8 + T cells downregulated the expression of SLC3A2 and SLC7A11 to promote tumor cell lipid peroxidation and ferroptosis." (PMID 34475496, 2021). "The epithelial (tumor) portion of the PDAC samples showed an increase in the expression of ATP13A3 (polyamine import) and SLC3A2 (diamine exporter) and lower expression of CAV1." (PMID 34945011, 2021). "Simultaneously, SLC3A2 depletion increases pro-survival autophagy in HNSCC, which helps tumor cells to survive on nutrient shortage and stress conditions." (PMID 33401748, 2021). "Four ferroptosis driver genes FLT3, ALOX12B, ALOX15, and VDAC2, had a low CNV, and four ferroptosis suppressor genes ACSL3, CISD1, FANCD2, and SLC3A2, had a high CNV, indicating that ferroptosis was inhibited in tumor development." (PMID 34434214, 2021). "IFN-γ released from immunotherapy-activated CD8+ T cells downregulates SLC3A2 and SLC7A11 expression, and increases tumor cell lipid peroxidation and ferroptosis, which ultimately improves anti-tumor efficacy of immunotherapy." (PMID 33815361, 2021). "For example: interferon-gamma (IFNγ) released by CD8+ T cells can down-regulate the expression of SLC3A2 and SLC7A1 in tumor cells, inhibiting the uptake of cystine, limiting tumor development and improving patient prognosis." (PMID 34869390, 2021). "Inhibiting the secretion of PD-L1-based exosome upregulated the IFN-γ level, which aided the downregulation of SLC3A2 and SLC7A11, two subunits to maintain the cysteine uptake by tumor cells." (PMID 34593794, 2021). "Using the same RNAsequencing data from ZCC and McGill University we assessed SLC3A2 expression in DIPG and found significantly higher SLC3A2 expression in DIPG tumor samples (n = 45) compared to fetal-derived normal brain tissue (n = 11)." (PMID 33579942, 2021). "Zou’s group further dissected the mechanisms of IFN-γ-regulated tumor cell ferroptosis and found that IFN-γ regulates tumor ferroptosis by targeting SLC7A11 and SLC3A2." (PMID 32245497, 2020). "When investigating within the molecular classes, high expression of SLC3A2 protein was predictive of shorter BCSS in ER+ high-proliferation class (p = 0.01), and TN tumours (p = 0.04)." (PMID 29545595, 2018).
tumor (continued). "Increased cell proliferation, tumor volume and weight with the SLC3A2-NRG1 fusion were significantly eliminated when a SLC3A2-NRG1Δ EGF truncated form was used in the same cancer cells." (PMID 27626312, 2016). "Studies indicate that CD8+ T cells activated by immunotherapy can downregulate the expression of XCT subunits SLC7A11 and SLC3A2 on tumor cell membranes through the secretion of interferon‐gamma (IFN‐γ), enhancing intracellular lipid peroxidation and leading to tumor cell ferroptosis." (PMID 41560416, 2026). "In the context of HNSC, we found that SLC3A2 was markedly overexpressed in tumor tissues compared to normal controls." (PMID 39926285, 2025). "A study elucidated that interferon-gamma (IFN-γ) released from CD8+ T cells can downregulate the expression levels of SLC3A2 and SLC7A11 on the tumor cell surface, thereby suppressing cystine uptake by tumor cells and ultimately promoting tumor cell lipid peroxidation and ferroptosis." (PMID 40260246, 2025). "Moreover, remarkable upregulation of SLC1A5, SLC3A2, and SLC7A5 were revealed by Western blotting in paired ESCC tumor and normal tissues." (PMID 39757767, 2025). "This suggests that the anti-tumor effects of disulfidptosis may involve immunomodulatory mechanisms, potentially through CD8+ T cell functional inhibition or SLC3A2/SLC7A11-mediated cystine metabolism regulation impacting immune escape in ESCC." (PMID 40303412, 2025). "Human protein array analyses identified cellular targets of XON9, such as solute carrier family 3 member 2 (SLC3A2), annexin A5 (ANXA5), fatty acid synthase (FASN) or reticulon 4 (RTN4) involved notably in tumor progression, angiogenesis, cell growth or apoptosis." (PMID 41009747, 2025). "High SLC3A2 expression predicts poor outcomes in PTCL, as SLC3A2‐mediated arginine uptake promotes the malignant behaviors of tumor cells and induces tumor immune escape, thereby fueling tumor progression." (PMID 40344476, 2025). "Furthermore, research has revealed that interferon-γ (IFN-γ) secreted by NK cells can significantly downregulate the mRNA and protein expression levels of SLC3A2 and SLC7A11, thus inducing ferroptosis in tumor cells." (PMID 40260246, 2025). "Furthermore, we evaluated the effect of the simultaneous knockdown of SLC1A5, SLC3A2, and SLC7A5 on tumor growth in a cell‐derived xenograft (CDX) mouse model." (PMID 39757767, 2025). "Also, SLC3A2-specific CAR T cells were shown to promote interferon-γ and interleukin-2 synthesis in vitro and enhance overall survival, while decreasing tumor growth." (PMID 38705513, 2024). "For example, in anti-PD-L1 immunotherapy, IFN-γ secreted by activated CD8+ T cells downregulates the expression of SLC3A2 and SLC7A11, impairs the uptake of cystine by tumour cells, and consequently promotes ferroptosis-specific lipid peroxidation in tumour cells." (PMID 38993573, 2024). "The utilization of PD-L1 blockers elicits the secretion of IFN-γ by CD8+T cells, leading to the inhibition of transcription and expression of SLC7A11 and SLC3A2, thereby reducing GPX4 production via the JAK1/STAT1 pathway and facilitating ferroptosis in tumor cells." (PMID 38853203, 2024). "However, CD8+T cells can also assume an antioxidant role by decreasing the M1/M2 macrophage ratio and enhancing SLC3A2 expression upon binding to TYRO3, which impedes tumor cell ferroptosis and fosters tumor progression." (PMID 38853203, 2024). "SLC3A2 has been shown to be one of the proteins involved in the polyamine transport pathway in NB, and in combination with DFMO (ODC1 inhibitor), was shown to inhibit tumor development in TH-MYCN transgenic mice." (PMID 38858548, 2024). "For instance, the expression levels of SLC3A2 and SLC7A11 may correlate with tumor sensitivity to ferroptosis inducers, serving as predictive factors for treatment outcomes." (PMID 39273090, 2024).
tumor (continued). "In addition, a combination of acidosis and metformin work synergistically to inhibit tumor progression and M1 polarization of macrophages through the ZFAND5/SLC3A2/ferroptosis pathway." (PMID 38705513, 2024). "The anti-tumor cytokine IFN-γ derived from CD8 T cells could downregulate the expression of SLC7A11 and SLC3A2, which further activate the ferroptosis pathway and exhibit anti-tumor effect." (PMID 37587262, 2023). "Interferon gamma (IFNγ) released from CD8+ T cells downregulates the expression of SLC3A2 and SLC7A11, two subunits of the glutamate-cystine antiporter system xc-, impairs the uptake of cystine by tumour cells and, as a consequence, promotes tumor cell lipid peroxidation and ferroptosis." (PMID 38201582, 2023). "Uptake of [18F]FSPG in tumor cells is related to protein expression of the xCT transporter, a glutamate–cystine exchanger (SLC7A11/SLC3A2 (4F2hc) heterodimer) that transports L-cystine (Cys-S-S-Cys) into the cell and L-glutamate to the extracellular compartment." (PMID 36961000, 2023). "In an in vivo xenograft model, SLC3A2-targeted CAR-T cells significantly improved overall survival and reduced subcutaneous xenograft tumor growth and tumor burden without weight loss and cytokine release syndrome (CRS)." (PMID 35935930, 2022). "Through the HPA database, we found that three genes, namely ABCC9, AHNAK, and DIP2C, had low expression in patients with tumours, and eight other genes—PLOD1, SLC3A2, RUNX2, RAD9A, CHMP4C, DARS2, CLIC3, and POU5F1—were highly expressed in patients with tumours." (PMID 36685927, 2022). "Eight genes (SLC3A2, DARS2, DIP2C, PLOD1, RUNX2, ABCC9, AHNAK, and CLIC3) may be involved in the malignant transformation of tumours, and three genes (CHMP4C, POU5F1, and RAD9A) may have a protective effect in patients with tumours." (PMID 36685927, 2022). "SLC3A2 was suppressed by IFN-γ that produced by activated CD8+ T cells, which resulted in a restriction of cystine uptake and then enhanced tumor lipid peroxidation and ferroptosis, and improved tumor control." (PMID 36386203, 2022). "Likewise, a known negative regulator of SLC3A2 expression, MARCH137, lost its tumor suppressor phenotype when glutamine was limiting." (PMID 36115844, 2022). "Furthermore, IFNγ downregulates the expression of SLC3A2 and SLC7A11, two subunits of the glutamate–cystine antiporter system xc−, impairs the uptake of cystine by tumor cells, and subsequently promotes tumor cell lipid peroxidation and ferroptosis." (PMID 34385592, 2022). "In addition, interferon gamma released by CD8+ T cells downregulates the expression of SLC3A2 and SLC7A11, impairing the uptake of cystine by tumor cells and thus promoting lipid peroxidation and iron weakness in tumor cells." (PMID 36012134, 2022). "Then, we analyzed the correlation between SLC3A2 expression and 60 immune check-point genes, of which 24 were stimulatory, like ICOS and CD28, while the other 36 genes were inhibitory for anti-tumor immunity, such as PD1 and PDL1 (CD274)." (PMID 35992269, 2022). "Another study revealed that CD8+ T cells released interferon-gamma (IFNγ) promoted ferroptosis-specific lipid peroxidation in tumor cells via downregulating the expression of SLC3A2 and SLC7A11, and in turn, increased ferroptosis contributes to the anti-tumor efficacy of immunotherapy." (PMID 35071242, 2021). "Manipulating such therapies to increase SLC1A5, SLC3A2, and SLC7A5 expression in the immune cells could enhance anti-tumor immunotherapy and lead to developments in the field." (PMID 33953707, 2021). "Moreover, IFNγ released by CD8+ T cells inhibits expression of SLC3A2 and SLC7A11 on tumor cells, leading to tumor ferroptosis." (PMID 33801234, 2021). "IFNG (interferon gamma, INFγ)released from CD8+ T cells downregulates the expression of SLC3A2 and SLC7A11, two subunits of the glutamate-cystine antiporter system xc-, inhibits the uptake of cystine by tumor cells, and consequently promotes tumor cell lipid peroxidation and ferroptosis." (PMID 34422642, 2021).
tumor (continued). "In addition, IFN-γ can downregulate the expression of two Glu-cystine antiporter subunits, recombinant solute carrier family 3, member 2 (SLC3A2) and SLC7A11, on the surface of tumor cells." (PMID 34123855, 2021). "SLC7A5 and SLC3A2 were expressed at relatively high levels in 22Rv1 castration-resistant orthografts following chronic ADT (modelling clinical castration-resistant disease), while SLC1A5 was preferentially expression in CWR22Res tumours following acute ADT." (PMID 33237350, 2020). "When investigated, ferroptosis in CD8 + T cells that is activated by cancer immunotherapy, the interferon-gamma (IFNγ), downregulates the expression of SLC3A2 and SLC7A11, impairs the uptake of cystine by tumor cells, and as a consequence, promotes tumor cell lipid peroxidation and ferroptosis." (PMID 32372896, 2020). "High SLC3A2 protein expression was associated with shorter DMFS (p < 0.001) and this was only observed in ER+ high-proliferation and TN tumours (p = 0.04) but not with other two subtypes." (PMID 29545595, 2018). "The fact that MYC controls glutamine uptake and catabolism through transcription of SLC3a2, SLC5A1, SLC7A1, and GLS1 in tumor cells indicates that additional signaling events are involved in determining the target preference of MYC between tumor cells and activated T cells." (PMID 28245597, 2017). "SL exposure also induced changes in the expression of genes involved in metabolic functions in tumor and stem cells (ALDH1B1, ABCB1, SLC3A2, SLC44A2, SLC31A2, SLC7A11, CYP24A1, PTGS2/COX2, PPRC1), cytokines (CCL3L3, GDF15) and growth and differentiation factors (PGF, TGFBR11 and FOXD1)." (PMID 24742967, 2014). "However, our in vitro genome‐wide immune screen results showed that knockout of Atf4, Ddit3, Slc7a11, or Slc3a2 alone did not significantly enhance tumor cell sensitivity to T cell–mediated killing." (PMID 41042068, 2025). "Therefore, we proposed that SLC3A2 could impact the progression and prognosis of NPC and HNSC by both influencing immune cell infiltration and directly affecting tumor cells." (PMID 39926285, 2025). "Interferon gamma (IFN-γ) released by CD8+ T cells downregulates the expression of two subunits, SLC3A2 and SLC7A11, of the glutamate-cysteine antiporter system, impairing tumor cell uptake of cysteine, thereby promoting lipid peroxidation and ferroptosis in tumor cells." (PMID 38753091, 2024). "Interestingly, IFNγ produced by activated CD8+ T cells inhibits the expression of SLC3A2 and Solute Carrier Family 7 Member 11 (SLC7A11), components of the cystine/glutamate antiporter system xc-, promoting lipid peroxidation and ferroptosis in tumor cells." (PMID 39273090, 2024). "In summary, SLC3A2 and SLC7A11, which play an important role in glutathione synthesis, play a role in resisting oxidative stress, protecting cells from iron-mediated death, and promoting the survival and metastasis of tumour cells through their respective effects." (PMID 37829798, 2023). "CD8+ T cells downregulate the expression of SLC3A2 and SLC7A11, two subunits of the glutamate–cystine reverse transport system Xc-, by releasing IFNγ, which in turn impairs cystine uptake by tumor cells, promoting tumor cell lipid peroxidation and the onset of ferroptosis." (PMID 36671532, 2023). "The levels of the main methionine transporters of CD4 T cells, including SLC7A5 and CD988, which form a heterodimeric structure comprising SLC7A5 and SLC3A2, were not markedly reduced in tumor-infiltrated CD4 T cells compared to those in CD4 T cells from tumor-free mice." (PMID 37147330, 2023). "However, unlike IRF1, IRF8 deletion did not change the expression of SLC3A2 or SLC7A11 in tumor cells." (PMID 36672246, 2023). "It has been shown that IFNγ released from CD8+ T cells downregulates the expression of two subunits (SLC3A2 and SLC7A11) of the glutamate-cystine reverse transporter system xc, which inhibits tumor cell cystine uptake and thus promotes lipid peroxidation in tumor cells." (PMID 37399661, 2023).
tumor (continued). "It remains possible that other tumor types may utilize cooperative RAS and SLC3A2." (PMID 36115844, 2022). "In addition, SLC3A2-KD failed to form tumor in vivo when orthotopically transplanted into immunocompromised mice." (PMID 35501367, 2022). "Interestingly, when comparing expression across all tumor samples versus all normal tissue samples, in contrast to SLC3A2 and SLC7A11, GPX4 was not significantly overexpressed in cancer tissues compared to normal tissues across the set." (PMID 33672555, 2021). "Similarly, SLC3A2 protein expression was associated with negative hormone status and HER2+ tumours (all p ≤ 0.001) and it was highly expressed in TN compared with non-TN tumours (p < 0.001)." (PMID 29545595, 2018). "In this mechanism, the increased levels of IFN-γ secreted from activated CD8+ T cells could suppress SLC3A2 and SLC7A11 (two important subunits of the glutamate-cystine antiporter system xc-) and restrain tumor cell cystine uptake, thus leading to lipid peroxidation and ferroptosis in tumor cells." (PMID 40539046, 2025). "Thus, SLC3A2/4F2hc (also known as CD98), the obligate interaction partner of LAT1, although not a transporter itself, is a potential target as well due to its elevated expression in various carcinomas and neoplasms, and as a consequence of intestinal inflammation." (PMID 36770817, 2023). "We observed that stable knockout of SLC3A2 and SLC7A5 effectively inhibited tumor growth in vivo, as reflected by a significant reduction in tumor size and growth rate compared to non-target CRISPR-V2 controls." (PMID 38267663, 2024). "Low proliferative, but not high proliferative, luminal tumours also showed a weak positive correlation between GLS2 protein and c-MYC (p < 0.001), SLC1A5 (p < 0.05) and SLC3A2 (p < 0.001)." (PMID 34439127, 2021). "In multivariate Cox regression analysis, SLC3A2 protein was a predictor of shorter BCSS (p < 0.001) independent of tumour size, grade and stage." (PMID 29545595, 2018).